AQP1 (aquaporin 1 (Colton blood group))
Diseases named in the same sentence as AQP1 in open-access papers (continued):
Sharing a sentence is not in itself a finding about the gene and the disease.
tumor (continued). "AQP1 levels also correlated with tumour size but not grade, raising the issue of potential detection of indolent renal masses that would never become clinically significant." (PMID 29610964, 2018). "AQP1 siRNA‐treated tumours exhibited decrease in high molecular weight DNA compared to that of negative control (untreated B16F10 cells) and CTRL siRNA‐treated tumours." (PMID 29044946, 2018). "It is speculated AQP1 enhances the activity of MMP2 and MMP9 through FAK and Wnt signalling pathways, augmenting migration of tumour cells and endothelial cells." (PMID 28146084, 2017). "AQP1 was not an independent prognostic factor in multivariate analysis stratified by age, tumor size and histological grade (P = 0.166)." (PMID 29245912, 2017). "Both RhoA and Rac1 are known to be involved in FAK-mediated tumour invasion and metastasis via Rho guanine exchange factor and the PI3K signalling pathway, and this may be one of the mechanisms whereby AQP1 influences the activities of Rho GTPases." (PMID 28146084, 2017). "A significant linear correlation exists between AQP1 protein concentrations and tumor size in proximal tubule originating tumors compared to nonsurgical controls." (PMID 24803718, 2014). "Since all of the tumour patients received dexamethasone, it was not possible to determine the effect of glucocorticoids on AQP1 expression." (PMID 12237771, 2002). "Additionally, AQP1 is also widely expressed in microvascular endothelial cells, including those in the kidney and tumor microvessels, as well as in non-vascular endothelial cells in the pleura, peritoneum, cornea, and lymphatic vessels." (PMID 39724420, 2025). "Combined treatment with the AQP1 water channel inhibitor AqB013 led to a further 20 to 40% reduction of invasion over Apamin alone, indicating key roles for ion channels such as SK2 in GBM tumor mechanisms, and supporting Apamin as a promising drug candidate in GBM therapy." (PMID 41308994, 2025). "Consequently, tumor cells displayed solitary cilia and lack of AQP1 expression, indicating similar defects in multiciliation and epithelial maturation in Sox2-deficient tumor cells." (PMID 40128799, 2025). "Therefore, it is hypothesized that elevated expression of AQP1 and AQP3 may facilitate tumor cell formation." (PMID 39440058, 2024). "Furthermore, we observed that Aqp1 expression had no detrimental effects on native biological activities, such as phagocytosis, immune response, insulin secretion, and tumor cell migration in the analyzed cell lines." (PMID 38649904, 2024). "Tumor markers with high sensitivity and specificity have not yet been validated for ccRCC screening, but some candidate molecules have been recently proposed, such as aquaporin 1 (AQP1) and perilipin 2 (PLIN2)." (PMID 37370817, 2023). "Further research is needed to fully understand the mechanisms by which AQP1 may or may not influence this aspect of tumor biology." (PMID 37762642, 2023). "Interestingly, irrespective of CAP treatment, tumor organoids were expressing 2-fold less Aqp1, Aqp4, and 10-fold less Aqp3 levels than normal organoids, whereas Aqp5 expression was increased." (PMID 35169122, 2022). "To verify this previously unknown cell-of-origin for pRCC, we recruited an independent pRCC cohort of 50 patients from Drum Tower hospital and performed immunofluorescence staining with the PT marker AQP1, the CD_PC marker GATA3 or GRHL2, on tumor samples from these patients." (PMID 35013217, 2022). "Thereby it is reasonable that the combination of AQP1 with RIPK1 at D324 sequence is an obligatory step for TNBC to facilitate the recruitment of caspase-8, aggravate the cleavage of RIPK1, sequester RIPK1 in a quiescent form, and finally unleash tumor progression." (PMID 33980862, 2021).
tumor (continued). "Previous studies have reported that four AQP family members (AQP1, AQP 3, AQP 4, and AQP 5) were expressed in lung tissues; therefore, we further explored the expression levels of these genes with different tumor stages for LUAD patients using UALCAN databases." (PMID 34708074, 2021). "A prospective study examining frozen tissue qRT-PCR of AQP1, DDX11, BAIAP2L1, and six previously identified genes (PBRM1, BAP1, SETD2, KDM5C, FOXC2, and CLIP4) showed that expression of DDX11 was a significant factor for predicting tumor aggressiveness based on Fuhrman grade." (PMID 31963294, 2020). "Therapies aimed at blocking transcriptional activation of AQP1 could impede cancer angiogenesis, if the treatment could be spatially limited to the tumor site without impacting normal cell functions." (PMID 29922644, 2018). "From the in vivo data, it is evident that AQP1 blockade may not be effective for reducing VM in vivo, perhaps due to individual variation and tumour cell heterogeneity." (PMID 29104239, 2017). "The ability of AQP1 to produce robust induction-dependent MRI contrast in tumour xenografts without affecting tumour growth suggests that this reporter gene could be useful for longitudinal imaging of gene expression in vivo." (PMID 28008959, 2016). "In vivo blockade of AQP1 had no biologically significant effect on growth of established tumours." (PMID 25821338, 2015). "Interestingly, AQP1 immunoreactivity was absent from the majority of canine tumor specimens studied." (PMID 24338153, 2014). "In addition to AQP1, AQP3 may also play a role in tumor angiogenesis." (PMID 39440058, 2024). "Furthermore, these analyses indicated that survival of patients with tumours expressing high APQ1 levels was shorter when compared to patients with low AQP1 expression and that the difference in survival was more significant in the case of joint high expression of AQP1 and CAV1." (PMID 32065471, 2020). "However, HIF‐1α dependent VEGF increase would not be able to induce the same level of tumour angiogenesis as that found in control tumours and this could be due to the slower cell migration of AQP1 silenced endothelial cells." (PMID 29044946, 2018). "While our sample size is too small to evaluate the correlation of either AQP1+MECA79+ vessel or aggregates with LN metastasis, it is clear that both LN positive and negative disease can exhibit primary tumor lymphoid aggregates in the treatment naïve setting." (PMID 38361951, 2024). "Tumor cells with GATA3 or GRHL2 positive nuclei also contain the pRCC marker cytokeratin 7 (CK7) in the cytoplasm, without any traces of AQP1." (PMID 35013217, 2022). "While we observe that some migrated tumor cells highly express CXCR4 other cells do not, we determined a dominant role of AQP1 in the migrating cells in the scratch assay." (PMID 33467498, 2021). "We probed for AQP1 and CD34 (to identify endothelial cells) and stained with hematoxylin and eosin (HE) to identify tumor and nontumor areas of the specimens." (PMID 32253832, 2020). "In the non-irradiated group, AQP1 and AQP4 were expressed in GSCs at basal levels and no significant changes were observed in their expression during tumor progression." (PMID 31803626, 2019). "Moreover, urinary levels of AQP1 and PLIN2 were observed to be correlated with the tumour size and stage but not with grade." (PMID 26482227, 2015). "According to the GEPIA database, AQP1, AQP3, AQP4, and AQP9 were significantly expressed in LUAD tissues compared to normal lung tissues (p < 0.05), but some genes including AQP0, AQP5, AQP6, AQP7, AQP8, AQP10, and AQP11 were not differentially expressed between tumor and normal tissues." (PMID 34708074, 2021).
cancer (93 papers, 2002 to 2026). A tumor composed of atypical neoplastic, often pleomorphic cells that invade other tissues. "Aquaporin-1 (AQP1), a water and solute channel, has been implicated not only in fluid homeostasis but also in cancer progression." (PMID 41463012, 2025). "In cancer cells, several reports linked excess expression of the protein, aquaporin 1 (AQP1), with apoptosis resistance." (PMID 39175041, 2024). "Latest research has linked AQP1 upregulation to several cancer types as an independent predictive marker." (PMID 38336645, 2024). "In cancer cells, high expression of aquaporin 1 (AQP1), a water channel, is associated with apoptosis resistance." (PMID 39175041, 2024). "Given the multifaceted roles of AQP1, from water transport to ion channel gating and its association with various types of cancer, the protein appears to be a critical player in both physiology and pathophysiology, including tumorigenesis." (PMID 37762642, 2023). "AQP1, a gene of Colton blood system, has prognostic significance in most cancer types, including the association of good outcomes in seven types of cancers, i.e., HNSC, SARC, LIHC, KIRP, KICH, MESO, KIRC and poor outcomes in three cancers (LUSC, LGG, UVM)." (PMID 35955933, 2022). "AQP1 was first discovered in erythrocytes and renal proximal tubules; it has been associated with pathological factors, such as cancer, inability to concentrate urine, and altered pain perception." (PMID 36532729, 2022). "Recently, over-expression of AQP1 has been associated with many types of cancer as a distinctive clinical prognostic factor." (PMID 28146084, 2017). "Establishment of AQP1 as a cancer biomarker potentially encourages screening and stratification of susceptible patients for early cancer diagnosis, prognostication of cancer patients and prediction of treatment efficacy." (PMID 28146084, 2017). "Mammalian AQP1 expression has been associated with migration and metastasis in aggressive cancers including colon, melanoma and breast cancers, astrocytoma and glioblastoma." (PMID 29099773, 2017). "The association between the expression of AQP1 and cancer progression have been reported." (PMID 36803413, 2023). "Importantly, we developed a three-gene panel based on genes associated with AQP1 DNA methylation to predict cancer risk and the prognosis of elderly CN-AML patients." (PMID 32373535, 2020). "Furthermore, higher AQP1 levels were associated with a better prognosis of cancer-specific and cancer-free survival." (PMID 32392781, 2020). "AQP1 channels have been well-documented in published studies to be linked to mechanisms of cell motility in other cancer types, and they have successfully been targeted by pharmacological agents that dramatically slowed cancer migration and invasiveness, as reviewed previously." (PMID 37760476, 2023). "Interestingly, chemotherapy appeared to result in increased AQP1 expression, which might, in theory, cause a counterproductive boost in cancer recurrence by enhancing invasiveness." (PMID 32679804, 2020). "The results showed that TPM downregulated AQP1 expression, inhibited CA activity, and prevented cancer metastasis by approximately 81.25%." (PMID 40283503, 2025). "Hoque and colleagues used immunohistochemistry to examine the distribution of AQP1 in different types of primary cancer and found that it was increased in 62% of adenocarcinoma and 75% of bronchoalveolar carcinoma." (PMID 38336645, 2024). "In the later phases of ovarian malignancies, the expression of the AQP1 protein was elevated, while cancer subgroups have varying degrees of either favourable or detrimental correlations with patient survival." (PMID 38336645, 2024). "This has motivated scientists to investigate the relationship between AQP1 and the biological processes of cancer." (PMID 38336645, 2024). "It was also revealed that cancer cells that overexpressed AQP1 were far more capable of cell motility, invasion, and metastasis." (PMID 38336645, 2024).
cancer (continued). "The levels of expression of AQPs 4, 8, and 11, assessed in sectioned EC tissues using immunohistochemistry, were weaker than that for AQP1 in both the low- and high-grade cancer tissues (H-scores < 100)." (PMID 37760476, 2023). "In some cases, variability was evident in AQP1 expression patterns within single cancer samples, suggesting heterogeneity within these tissue samples (Pt.4, Pt.5 and Pt.7)." (PMID 37760476, 2023). "The link between AQP1 and cancer progression has garnered significant attention, leading to numerous reviews on the subject." (PMID 37762642, 2023). "AQP1 expression was confirmed by quantitative PCR and immunohistochemistry of fixed paraffin-embedded cancer tissues." (PMID 37760476, 2023). "The primary outcome of this work was the novel demonstration that AQP1 ion channel inhibitors restrained the invasiveness of EC cell lines and primary cancer cells from both low- and high-grade EC grades." (PMID 37760476, 2023). "The involvement of AQP1 in cancer migration and invasion is of great significance, as these processes play pivotal roles in human carcinogenesis." (PMID 37904849, 2023). "Interaction of cyclic GMP (involved in tumorigenesis and metastasis of cancers such as colon, breast, and cervical) with the intracellular gating loop of AQP1 opens the AQP1 central pore and serves as the site of action by the inhibitor AqB011." (PMID 37760476, 2023). "AQP1 ion channel inhibitors reduced invasiveness of human primary EC cancers established from both low- and high-grade tumors." (PMID 37760476, 2023). "It is noteworthy that AQP1 has demonstrated divergent effects on migration in different types of cancer (Moon, Moon & Kang, 2022)." (PMID 37904849, 2023). "The observed inter- and intra-tumoral heterogeneity and interpatient variability of AQP1 expression emphasizes the importance of combining multiple approaches in cancer treatment." (PMID 37760476, 2023). "TNBC cells typically have high levels of AQP1 and low levels of RIPK1, which is associated with aggressive cancer features and poor prognosis." (PMID 38136293, 2023). "So far, four AQPs (AQP1, AQP4, AQP5, and AQP9) have been linked to EMT in several cancer cell models." (PMID 35847914, 2022). "AQP1, a Colton blood group antigen system gene, is over-expressed in a variety of human cancers, including brain, breast, lung and nasopharyngeal cancers." (PMID 35955933, 2022). "In light of their physiological relevance, the AQP1–protein complexes are anticipated to be key players in various diseases, especially in cancer, and to be considered as potential targets for new therapeutic options." (PMID 36077012, 2022). "AQP1 in atherosclerotic lesions and malignant tumors has been suggested to promote plaque progression and angiogenesis." (PMID 35163313, 2022). "Briefly, the high expression of seven blood group antigen genes, i.e., FUT7, AQP1, P1, C4A, AQP3, KEL, and DARC, was significantly associated with good prognosis in six types of cancers, i.e., KIRC, HNSC, LUAD, CESC, SARC, MESO." (PMID 35955933, 2022). "Increased AQP1 expression has been suggested to facilitate the progression from cervical intraepithelial neoplasia to cancer." (PMID 33499000, 2021). "AQP1 has been shown to be expressed in proliferating malignant tumor cells as well as to play an important role in micro-vessel formation." (PMID 33644043, 2021). "A quantitative transcriptomic analysis of AQP1-10 in human cancer biopsies similarly showed that increased transcript levels of AQPs 1, 3, 5 and 9 were most frequently associated with poor survival." (PMID 32679804, 2020). "A link between disease severity and upregulation of aquaporin-1 (AQP1) expression in certain cancer types has been documented previously." (PMID 31477744, 2019). "In aggressive cancers including subtypes of colorectal cancers, gliomas, lung adenocarcinoma, laryngeal cancer and cholangiocarcinomas, AQP1 channels are upregulated." (PMID 31477744, 2019).
cancer (continued). "Inhibition of AQP1 channel activity is a strategy of interest for potential therapeutic control of metastasis in AQP1-expressing cancers." (PMID 31477744, 2019). "In summary, AQP1 water and ion fluxes appear to have a coordinated role in facilitating AQP1-dependent cancer cell migration." (PMID 31477744, 2019). "Results here showed that efficacy of AqB011 in impairing motility required the plasma membrane localization of AQP1 in the cancer cells." (PMID 31477744, 2019). "Simultaneous targeting of both the water and ion channel functions of AQP1 appears to offer opportunities to control cancer metastasis at lower doses and across more diverse classes of cancers than would be possible with single agents alone." (PMID 31477744, 2019). "The current study demonstrated two bumetanide-derived inhibitors of AQP1, AqB013 and AqB050, inhibit tube formation in vitro using murine and human endothelial cell lines known to express AQP1, supporting their potential utility as cancer therapeutics." (PMID 31013775, 2019). "In summary, AQP1 water fluxes and ion conductance appear to exhibit a coordinated role in facilitating cell migration in AQP1-dependent cancer cell lines." (PMID 31477744, 2019). "Prior reports have focused on measuring effects of single AQP1 modulators using two-dimensional wound closure assays of cancer lines." (PMID 31477744, 2019). "Future work is needed to explore effects of AQP1 inhibitors on other cancer cell types, to optimize bacopaside-related compounds for modulating AQP1 water flow, and to test the effectiveness of AQP1 agents in restraining metastasis in vivo." (PMID 31477744, 2019). "Over-expression of AQP1 has been observed in multiple human cancers including those of biliary tract, bladder, brain, breast, cervix, colon, nasopharynx, lung and prostate." (PMID 31013775, 2019). "Regarding the role of AQP1 in cancer cells, previous studies have shown that the expression of AQP1 is correlated with cell proliferation, migration, and angiogenesis in several cancers." (PMID 30042826, 2018). "Evidence is thus accumulating based on our own work and others to suggest that AQP1 is a prime target for anti-cancer therapy." (PMID 29495367, 2018). "Expression of aquaporin-1 (AQP1) in endothelial cells is critical for their migration and angiogenesis in cancer." (PMID 29495367, 2018). "Previous studies reported that AQP1 also has a role of cell migration and invasion in various cells, including cancer cells." (PMID 30042826, 2018). "Recent reports using immunofluorescence analyses have shown that the localization of AQP1 was in the cell surface membrane and/or the cytoplasm in various cancer cells." (PMID 30042826, 2018). "In mice, they observed that AQP1 expression increased cancer cell extravasation and lung metastases." (PMID 28146084, 2017). "This, however, is the first review the authors are aware that is dedicated to discussion on the significance of AQP1 in cancer biology." (PMID 28146084, 2017). "Despite the extensive literature supporting the involvement of AQP1 in cancer development and progression, the exact signalling pathways involved are yet to be elucidated." (PMID 28146084, 2017). "AQP1 is a strong cancer biomarker candidate and further research to elucidate the tumorigenic properties of AQP1 is awaited." (PMID 28146084, 2017). "AQP1 is over-expressed in multiple human cancers including that of biliary duct, bladder, brain, breast, cervix, colon, lung, nasopharynx and prostate." (PMID 28146084, 2017).